FGF21 (fibroblast growth factor 21)
Diseases named in the same sentence as FGF21 in open-access papers (continued):
Sharing a sentence is not in itself a finding about the gene and the disease.
sarcopenia (continued). "Nevertheless, it is known that FGF-21 impairs the function of satellite cells by alteration of the PI3K/Akt pathway, which leads to worse muscle fibre regeneration and, in consequence, to sarcopenia." (PMID 41010737, 2025). "Regarding muscle mass, older people with sarcopenia have higher circulating FGF21 levels than those without." (PMID 40171198, 2025). "A cross-sectional study demonstrated a significant decrease in serum FGF19 levels and a significant increase in serum FGF21 levels among elderly individuals with sarcopenia compared to those without sarcopenia." (PMID 38902808, 2024). "In conclusion, we analyzed the correlation between sarcopenia and FGF21 based on the paucity of original studies, and there is no strong evidence yet for a direct relationship between FGF21 and sarcopenia." (PMID 37386374, 2023). "Additionally, some mitokines potentially function as biomarkers for the diagnosis of sarcopenia, such as growth differentiation factor 15 (GDF15) and fibroblast growth factor 21 (FGF21)." (PMID 34881083, 2021). "This review describes the principal pathways controlling mitochondrial quality, many of which are potential therapeutic targets against muscle aging, and the connection between mitochondrial dysfunction and the myomitokines FGF21 and GDF15 in the pathogenesis of aging sarcopenia." (PMID 33374852, 2020). "A promising but not yet demonstrated biomarker of acute sarcopenia might be myokine fibroblast growth factor 21 (FGF21)." (PMID 39458423, 2024). "Whether FGF21 is a potential biomarker for the diagnosis of sarcopenia has not yet been confirmed by the strong results of studies." (PMID 37386374, 2023). "Contrary to our expectations, stool zonulin, stool calprotectin and serum LBP, sCD14, IGF‐1, myostatin, FGF‐21, irisin and DAO were comparable in cirrhotic patients with and without sarcopenia and in controls with and without sarcopenia (P > 0.05)." (PMID 37767786, 2023).
Cirrhosis (29 papers, 2013 to 2026). A chronic disorder of the liver in which liver tissue becomes scarred and is partially replaced by regenerative nodules and fibrotic tissue resulting in loss of liver function. "According to another study, serum FGF21 expression was predominantly upregulated in patients with severe ICU cirrhosis and had an important diagnostic value in patients with ACLF." (PMID 36440004, 2022). "However, serum FGF21 levels were decreased in CHB patients especially in those who developed cirrhosis and were associated with hepatic protein synthesis capacity." (PMID 29184085, 2017). "For instance, the FGF21‐agonist efruxifermin was recently shown to have potential for cirrhosis reversal." (PMID 41451774, 2026). "Fibroblast growth factor 21 (FGF21) is a mediator of liver metabolism and a marker of mitochondrial dysfunction and cirrhosis; therefore, we examined the FGF21 protein levels." (PMID 40381698, 2025). "FGF21 is a mediator of liver metabolism and a marker of mitochondrial dysfunction and cirrhosis, a potential biomarker for predicting ALD severity." (PMID 40381698, 2025). "Both serum and hepatic levels of FGF21 are elevated in patients with hepatitis, hepatic cirrhosis, and HCC." (PMID 39211324, 2024). "There was statistically significant differences between healthy, NAFLD and cirrhosis groups both when comparing FGF21 levels measured in peripheral and liver vein samples (p = 0.002)." (PMID 37078380, 2023). "Increased abundance of Eggerthella has also been found in patients with sarcopenic cirrhosis and was correlated with the level of fibroblast growth factor 21 in cirrhosis patients." (PMID 35002971, 2021). "In patients with hepatitis, fatty degeneration, cirrhosis and liver tumors, FGF21 levels in hepatocytes or phenotypically normal hepatocytes are invariably elevated compared to normal health subjects." (PMID 23590285, 2013). "Thirdly, patients with NAFLD and cirrhosis had high levels of FGF21." (PMID 37078380, 2023). "FGF21 secretion is reduced in chronic HBV infection, particularly in cirrhosis and the administration of FGF21 in HBV infected patients could improve liver inflammation and fibrosis." (PMID 35355551, 2022). "A decrease in serum FGF21 was observed with cirrhosis when the liver synthesis function was decreased, suggesting that a specific behavior of FGF21 may result in cirrhosis." (PMID 36440004, 2022). "Additionally, Akero therapeutics reported that efruxifermin (EFX), an FGF21-targeting drug, demonstrated a 39% reversal of cirrhosis in a Phase 3 study compared to only 15% in the placebo group, further emphasizing the potential of novel therapeutic interventions." (PMID 40244247, 2025). "Along with DM, higher BMI, lower FGF-21 (P = 0.055), and higher AFABP, together with HOMA-IR levels (P < 0.001) showed correlation with more serious fibrosis/cirrhosis during antiviral therapy in people infected with CHB and received a 3.7-fold high risk of more serious fibrosis and cirrhosis." (PMID 31915709, 2019). "Enterocytes: IPA analysis showed significant activation of inflammatory pathways (TNF, IFNG), PPARG/A with gut-liver signaling pathways (FGF21, IGF1R, CREBP) and fatty acid and lipid oxidation in compensated cirrhosis versus controls." (PMID 38369527, 2024). "In fact, studies in patients with MASH and fibrosis have shown the efficacy of some FGF21 analogs in improving fibrosis as well as resolving MASH, and other studies are ongoing in patients with cirrhosis." (PMID 39409124, 2024). "Baseline FGF21 concentrations were higher in NAFLD (200 ± 35 pg/mL, 2.2‐fold increase) and highest in cirrhosis (258 ± 46 pg/mL, 2.9‐fold increase, p = 0.005)." (PMID 37078380, 2023). "All the 9 patients with HCC had an FGF21 level over 200 pg/ml, whereas the median serum FGF21 levels in CHB and CHB-cirrhosis were 142.8 and 90.2 pg/ml, respectively." (PMID 29184085, 2017).
Cirrhosis (continued). "Circulating FGF-21 levels were higher in NAFLD patients than controls, which may be possibly attributed to those with advanced disease (NASH and related cirrhosis)." (PMID 40465044, 2025). "Higher circulating FGF-21 levels were shown in patients with NAFLD, which may be possibly attributed to those with advanced disease (NASH and or NASH-related cirrhosis)." (PMID 40465044, 2025). "The evidence of FGF21 concentrations being mostly driven by age and metabolic factors might also explain our finding of similar FGF21 concentrations in NAFLD and cirrhosis, despite tremendous differences in disease severity." (PMID 37078380, 2023). "Circulating levels of FGF21 are elevated in patients with alcoholic steatohepatitis but not cirrhosis, implying interplay between hepatic fat content and FGF21 expression." (PMID 27498701, 2016). "FGF21 was increased in NAFLD and cirrhosis independent of sampling from the liver vein versus peripheral blood." (PMID 37078380, 2023). "Compared with healthy, FGF21 concentrations were more than twice as high in patients with NAFLD and even higher in cirrhosis, although the difference between NAFLD and cirrhosis was not statistically significant." (PMID 37078380, 2023). "Notably, in another subgroup analysis, higher FGF-21 between patients with NAFLD and controls was observed within studies that included patients with NASH-related cirrhosis than those that did not include them." (PMID 40465044, 2025).
diabetic nephropathy (27 papers, 2015 to 2025). "Since disruption of glycolipid metabolism is the primary cause of diabetic nephropathy, we investigated the impact of FGF21 on this process." (PMID 39830349, 2024). "Fibroblast growth factor 21 (FGF-21) levels were elevated by the pathogenic process of diabetic kidney disease." (PMID 35528011, 2022). "FGF21 is mainly excreted by kidney, and serum FGF21 concentration is associated with the residual renal function in diabetic nephropathy." (PMID 31543863, 2019). "In patients with diabetic nephropathy, FGF21 levels are also independently associated with urinary albumin excretion, although studies on direct renal effects of FGF21 remain limited." (PMID 26594197, 2015). "This suggests that by promoting PAI-1 expression, FGF21 may be able to lower the risk of secondary thrombosis and delay the onset of diabetic nephropathy." (PMID 39830349, 2024). "Early-stage diabetic nephropathy is intimately linked to FGF21." (PMID 39830349, 2024). "This indicates that via regulating CDK1 to regulate the cell cycle in renal tissues, FGF21 is likely to slow down the mitotic catastrophe and, consequently, the progression of diabetic nephropathy." (PMID 39830349, 2024). "According to the information above, FGF21 was able to reduce inflammation and oxidative stress that accompanied the metabolism of glycolipids in diabetic nephropathy mice." (PMID 39830349, 2024). "This indicates that FGF21 can alleviate renal fibrosis, slow down fibrin deposition, and activate the fibrinogen activation pathway in diabetic nephropathy mice." (PMID 39830349, 2024). "Of note, the authors demonstrated a critical role of Fibroblast Growth Factor 21 (FGF21) in the protection conveyed by FF against diabetic nephropathy, as well as the activation of NRF2 through Akt2 signaling." (PMID 38474282, 2024). "In summary, our study discovered that FGF21 was significantly associated with worse renal outcomes in various renal diseases including CKD and diabetic nephropathy." (PMID 37009852, 2023). "FGF21 protects kidney from damage by alleviating renal lipid accumulation and inhibiting inflammation, and fibrosis effects in diabetic nephropathy." (PMID 34675822, 2021). "Studies have found that FGF21 levels can be used as a biomarker related to the prognosis of patients with diabetic nephropathy." (PMID 34675822, 2021). "Fenofibrate (FF) protects against diabetic nephropathy (DN) in type 1 diabetic (T1D) mice by upregulating the expression of fibroblast growth factor 21 (FGF21), leading to the activation of the Akt-mediated Nrf2 antioxidant pathways." (PMID 32025205, 2020). "Exogenous FGF21 treatment had been shown to suppress renal lipid accumulation and prevent diabetic nephropathy in animal studies." (PMID 30127382, 2018). "Fibroblast growth factor 21 (FGF21) is an endocrine-acting hormone that has the potential to treat diabetic nephropathy." (PMID 28676059, 2017). "While there is a lack of research on whether FGF21 can affect the progression of DN by regulating the cell cycle in diabetic nephropathy, this article is based on this to explore the novel mechanism of FGF21 in the treatment of diabetic nephropathy." (PMID 39830349, 2024). "In short, FGF21 improved the development of diabetic nephropathy in diabetic nephropathy-affected animals by reducing glomerular filtration damage, inflammation, and oxidative stress, inhibiting the formation of thrombus, and controlling the cell cycle through CDK1." (PMID 39830349, 2024). "Xu found a negative correlation between serum FGF21 content and PINP in patients with diabetic nephropathy through a cross-sectional study, suggesting that FGF21 may have a certain negative regulatory effect on bone formation." (PMID 39296716, 2024). "This shows that in the early stages of diabetic nephropathy, FGF21 may have a preventative and ameliorative effect." (PMID 39830349, 2024).
diabetic nephropathy (continued). "Our meta-analysis conducted to determine the association between FGF21 and renal function included various renal diseases such as CKD and diabetic nephropathy, which provides sufficient evidence for the inverse relationship between high FGF21 and the health of the kidney." (PMID 37009852, 2023). "In addition to diabetic macroangiopathy, FGF21 also plays a role in diabetic microangiopathies such as diabetic retinopathy and diabetic nephropathy." (PMID 36594101, 2023). "Furthermore, previous studies have found that FGF21 has a protective effect on the kidney by inhibiting inflammation and fibrosis in low-protein diet-induced renal damage and in diabetic nephropathy." (PMID 37724523, 2023). "FGF21 is also essential in slowing the progression of diabetic nephropathy." (PMID 37576954, 2023). "After 3-month FGF21 treatment, severe renal dysfunction, morphological changes, inflammation, apoptosis, and fibrosis observed in OVE26 mice were significantly attenuated, indicating, for the first time, that FGF21 induces a therapeutic effect on diabetic nephropathy in OVE26 mice." (PMID 35677107, 2022). "Systemic knockout of the FGF21 gene in mice with diabetic nephropathy resulted in more severe kidney damage, while administration of FGF21 to mice with the same pathology attenuated the nephropathy phenotype due to decreased renal lipid accumulation and oxidative stress." (PMID 33828528, 2021). "In addition to normalizing lipid profiles and insulin resistance, FGF21 also proved beneficial in diabetic nephropathy by improving lipid metabolism in the kidney as well as ameliorating oxidative stress." (PMID 33828528, 2021). "A cross-sectional study also confirmed that elevated serum FGF21 level may be a useful biomarker for predicting the progression of kidney disease, especially in the early stage of diabetic nephropathy." (PMID 34675822, 2021). "Furthermore, clinical studies have demonstrated that the levels of circulating FGF21 increased significantly in patients with early diabetic nephropathy and hypertensive nephropathy." (PMID 34773993, 2021). "As a metabolic regulator in glucose and lipid homeostasis, FGF21 could be involved in diabetic kidney disease." (PMID 30127382, 2018). "Furthermore, the FGF21 level is an independent biomarker of rapid CKD progression in patients at early stages of diabetic nephropathy." (PMID 28582462, 2017). "However, the increased level of FGF21 in diabetic nephropathy patients may be due to the increased compensatory secretion of FGF21 in the body due to the presence of FGF21 resistance." (PMID 37576954, 2023). "Moreover, it is worth noting that some clinical studies have found a significant increase in circulating FGF21 levels in patients with various kidney diseases, including renal transplantation, early diabetic nephropathy, acute renal insufficiency and long-term peritoneal dialysis." (PMID 34773993, 2021). "Therefore, our data also indicated that the LPD might protect against diabetic nephropathy both indirectly and directly via FGF21 induction." (PMID 29507597, 2018). "Diabetic nephropathy was induced in C57BL/6J mice by injection of STZ after high-fat 4, followed by subcutaneous injection of FGF21 for 4 weeks of treatment." (PMID 39830349, 2024). "Through upregulating the expression of FGF21 and activating Akt2/GSK-3β/Fyn/Nrf2 antioxidants and the AMPK pathway, fenofibrate can exert a role in preventing diabetic nephropathy in the patients with type 1 diabetes." (PMID 34675822, 2021). "Fibroblast growth factor 21 (FGF21) is a regulator of glucose homeostasis, and is suggested to have protective effect on diabetic nephropathy." (PMID 30127382, 2018). "Another possible explanation is that elevated FGF21 is a compensation to impaired renal function in subjects with CKD, similar to the response to tissue resistance observed in diabetic nephropathy." (PMID 30127382, 2018).
diabetic nephropathy (continued). "Furthermore, FGF21 administration decreases cholesterol and triglyceride accumulation in the diabetic kidney, and markedly abolishes the increase of p65 protein in the proinflammatory NF-κB pathway, all contributing factors to the progression of diabetic nephropathy." (PMID 26594197, 2015). "It was also shown that FGF21 dramatically reduces the expression of CDK1, which may help diabetic nephropathy by averting mitotic catastrophe and changing the renal cell cycle." (PMID 39830349, 2024). "The LPD prevented the progression of diabetic status; this effect may have been associated with the reduction of FW and the elevation of plasma FGF21 and HMW adiponectin, as well as UCP1 expression in BAT, resulting in suppression of diabetic nephropathy." (PMID 29507597, 2018). "FGF21 has been shown to ameliorate diabetic nephropathy, and in addition FGF-21-treated mice impeded mitogenicity, whereas it is unclear whether FGF21 can influence DN progression by regulating the cell cycle in diabetic nephropathy." (PMID 39830349, 2024).